CUL7 (cullin 7)
Description:
Core component of the 3M and Cul7-RING(FBXW8) complexes, which mediate the ubiquitination and subsequent proteasomal degradation of target proteins. Core component of the 3M complex, a complex required to regulate microtubule dynamics and genome integrity. It is unclear how the 3M complex regulates microtubules, it could act by controlling the level of a microtubule stabilizer. Interaction with CUL9 is required to inhibit CUL9 activity and ubiquitination of BIRC5. The Cul7-RING(FBXW8) complex also mediates ubiquitination and consequent degradation of target proteins such as GORASP1, IRS1 and MAP4K1/HPK1. Ubiquitination of GORASP1 regulates Golgi morphogenesis and dendrite patterning in brain. Mediates ubiquitination and degradation of IRS1 in a mTOR-dependent manner: the Cul7-RING(FBXW8) complex recognizes and binds IRS1 previously phosphorylated by S6 kinase (RPS6KB1 or RPS6KB2). The Cul7-RING(FBXW8) complex also mediates ubiquitination of MAP4K1/HPK1: recognizes and binds autophosphorylated MAP4K1/HPK1, leading to its degradation, thereby affecting cell proliferation and differentiation. Acts as a regulator in trophoblast cell epithelial-mesenchymal transition and placental development. While the Cul7-RING(FBXW8) and the 3M complexes are associated and involved in common processes, CUL7 and the Cul7-RING(FBXW8) complex may have additional functions. Probably plays a role in the degradation of proteins involved in endothelial proliferation and/or differentiation.
Synonyms: CUL-7; KIAA0076; dJ20C7.5; 3M1
Tractability: PROTAC: UniProt records ubiquitination sites on it; ubiquitination databases record sites on it; its protein half-life has been measured.
Safety:
Unwanted effects reported when the protein is acted on. In parentheses: how it was acted on, where the effect was seen, and who reports it.
neutropenia (source: ClinPGx)
Gene: Protein-coding gene on chromosome 6 (43,037,617 to 43,053,943, reverse strand). Ensembl gene ENSG00000044090.
Subcellular location: Cytoplasm; Cytoplasm, cytoskeleton, microtubule organizing center, centrosome; Cytoplasm, perinuclear region; Golgi apparatus
Pathways (Reactome):
Cellular responses to stimuli: XBP1(S) activates chaperone genes
Immune System: Antigen processing: Ubiquitination & Proteasome degradation
Metabolism of proteins: Neddylation
Gene Ontology:
Molecular function: protein binding; ubiquitin ligase complex scaffold activity; ubiquitin protein ligase binding
Biological process: epithelial to mesenchymal transition; microtubule cytoskeleton organization; mitotic cytokinesis; negative regulation of insulin receptor signaling pathway; placenta development; positive regulation of dendrite morphogenesis; protein ubiquitination; regulation of mitotic nuclear division; ubiquitin-dependent protein catabolic process; Golgi organization; proteolysis; SCF-dependent proteasomal ubiquitin-dependent protein catabolic process; vasculogenesis
Cellular component: 3M complex; centrosome; Cul7-RING ubiquitin ligase complex; cytoplasm; Golgi apparatus; perinuclear region of cytoplasm; plasma membrane; anaphase-promoting complex; cytosol; SCF ubiquitin ligase complex; cullin-RING ubiquitin ligase complex
Genetic constraint (gnomAD): Loss-of-function variants: 91 observed, 174.73 expected, observed/expected ratio (o/e) 0.52, 90% interval 0.44 to 0.62. The upper end of that interval is the gene's LOEUF score, 0.62, which puts it in group 2 of 6, group 1 being the genes least tolerant of losing a copy. Missense variants: 1,875 observed, 2,252.7 expected, observed/expected ratio (o/e) 0.83, 90% interval 0.8 to 0.87. Synonymous variants: 817 observed, 922.6 expected, observed/expected ratio (o/e) 0.89, 90% interval 0.83 to 0.94.
Homologues: Orthologues: chimpanzee CUL7 (99% identical), macaque CUL7 (97% identical), dog CUL7 (88% identical), rabbit CUL7 (86% identical), pig CUL7 (83% identical), rat Cul7 (80% identical), guinea pig CUL7 (78% identical), mouse Cul7 (78% identical). Paralogues in human: CUL9 (59% identical).
Diseases named in the same sentence as CUL7 in open-access papers:
CUL7 is named in the same sentence as 55 diseases in open-access papers, as found by Europe PMC text mining. Sharing a sentence is not in itself a finding about the gene and the disease. The quoted sentences say what the papers report.
3M syndrome (26 papers, 2012 to 2026). 3M syndrome is a primordial growth disorder characterized by low birth weight, reduced birth length, severe postnatal growth restriction, a spectrum of minor anomalies (including facial dysmorphism) and normal intelligence. "A total of 14 Chinese children diagnosed with CUL7 variant-caused 3M syndrome (excluding 4 prenatal cases) have been reported in the literature." (PMID 41234413, 2025). "Overall, no specific genotype-phenotype associations have been found in Chinese patients with 3M syndrome caused by CUL7 variants." (PMID 41234413, 2025). "Taken together, the diagnosis of 3M syndrome-1 caused by novel compound heterozygous variants in the CUL7 gene was made in this patient." (PMID 41234413, 2025). "Herein, we describe a Chinese patient with 3M syndrome caused by novel biallelic pathogenic variants in CUL7 from a non-consanguineous family, expanding the genetic spectrum of CUL7 in the Chinese population." (PMID 41234413, 2025). "CUL7 is the most prevalent pathogenic gene, and pathogenic variants in CUL7 have been identified in more than 65% of patients with genetically confirmed 3M syndrome." (PMID 41234413, 2025). "A mutation in the Cul7 gene is associated with 3M syndrome, an autosomal-recessive disease that causes growth and muscle abnormalities." (PMID 38334627, 2024). "No data on fertility are available apart from a study on the Yakut population that reported offspring with normal height in 2 men and 1 woman with 3-M syndrome caused by CUL7 pathogenic variants." (PMID 38847008, 2024). "Here, we summarize the clinical features and auxiliary examination results of four patients with 3M syndrome from four Chinese families, and report one novel variant each in CUL7 and OBSL1, expanding the molecular spectrum of the syndrome." (PMID 37719700, 2023). "Here, we describe the case of a Chinese family whose first fetus was prenatally diagnosed with 3M syndrome due to two novel CUL7 variants." (PMID 37877343, 2023). "Another case report described developmental delay, and hearing loss in a patient with 3M syndrome due to co-existence variants in CUL7 and ILDR1 gene." (PMID 37520055, 2023). "CUL7 mutations account for 70% of 3M syndrome cases, with the remainder caused by mutations in OBSL1 and CCDC8 occurring in a mutually exclusively manner between these three genes." (PMID 35982156, 2022). "Recently, several novel CUL7 mutations have been discovered in 3-M syndrome, expanding our knowledge of phenotype-genotype correlations in this disease." (PMID 33130829, 2020). "They noted that, in terms of the clinical and biochemical 3M syndrome phenotype, children with CUL7 mutations were significantly shorter than those with OBSL1 or CCDC8 mutations." (PMID 32235515, 2020). "A majority of disease-causing mutations for human 3M syndrome are located within one of three genes, with approximately 70% of cases occurring within the CUL7 gene, 25% in the OBSL1 gene and 5% within the CCD8 gene." (PMID 32933480, 2020). "In conclusion, we identified novel truncating mutations of CUL7 in a Japanese patient with 3M syndrome." (PMID 32047638, 2020). "While cullin-7 mutations are responsible for approximately 77.5% of 3M-syndrome cases, mutations in obscurin-like 1 (Obsl1) and Ccdc8 have also been shown to be associated with the syndrome." (PMID 33114658, 2020). "Further studies are ongoing and will hopefully shed light on the pathogenic function of CUL7 in 3‐M syndrome." (PMID 32141654, 2020). "The 3M syndrome is caused by loss-of-function mutations in the genes encoding cullin 7 (CUL7), obscurin-like 1 (OBSL1), and coiled-coil domain containing protein 8 (CCDC8)." (PMID 27796265, 2017). "CUL7 appears to be the major gene responsible for 77% of 3M syndrome, while OBSL1 mutations account for a relatively small percentage of 16%." (PMID 27796265, 2017).
3M syndrome (continued). "Our previously published transcriptomic data from 3-M syndrome patients with null mutations in either CUL7, OBSL1 or CCDC8 revealed that IGF2 expression is significantly reduced." (PMID 24711643, 2014). "Recent work with a short stature syndrome, called 3 M Syndrome, has linked CUL7 to growth in humans." (PMID 23029530, 2012). "OMIM 273750 (3-M syndrome) is a rare autosomal recessive condition caused by homozygous or compound heterozygous pathogenic variants in genes encoding cullin 7 (CUL7; type 1: MIM *609577), obscurin-like 1 (OBSL1; type 2: MIM *612921), or coiled-coil domain containing 8 (CCDC8; type 3: MIM *614205)." (PMID 38847008, 2024). "The diagnosis of 3M syndrome could be confirmed by identifying biallelic variants in CUL7, OBSL1, or CCDC8." (PMID 37877343, 2023). "Exome sequencing revealed that two patients with 3M syndrome had homozygous variants of the CUL7 gene: one novel pathogenic variant and one previously reported pathogenic variant; the other two patients were heterozygous for variants in OBSL1, one of which had not been reported previously." (PMID 37719700, 2023). "The mitosis and cytokinesis defects caused by loss of CUL7 function may be related to the growth retardation observed in patients with 3M syndrome." (PMID 37719700, 2023). "However, the vertebrate-specific CRL7FBXW8 is of interest because it eludes existing models, yet its constituent cullin CUL7 and F-box protein FBXW8 are essential for development, and CUL7 mutations cause 3M syndrome." (PMID 35982156, 2022). "Mutations in cullin-7 are specifically associated with patients presenting the 3M-syndrome, an autosomal recessive disorder characterized by pre- and post-natal growth deficiencies that may involve muscles." (PMID 33114658, 2020). "Although we could not assess the transcripts from both abnormal alleles, the biallelic loss-of-function mutations of CUL7 in our patient were believed to perturb mitosis and cytokinesis, resulting in the 3M syndrome phenotype." (PMID 32047638, 2020). "Since the reported role of CCDC8 mutations in 3-M syndrome links it to Obsl1 and E3 ligase Cul7, we tested whether Obsl1 or Cul7 could also inhibit HIV-1 production." (PMID 26423533, 2015). "In addition, researchers have found that mitotic and cytokinesis defects caused by loss of CUL7 function may be associated with short stature in patients with 3M syndrome." (PMID 37719700, 2023). "As a result, the mechanism by which CUL7 deficiency causes 3M syndrome remains unclear." (PMID 37877343, 2023). "Consequently, fetal WES was performed, which revealed two novel biallelic CUL7 variants that could explain the prenatal ultrasound results and facilitate the prenatal diagnosis of 3M syndrome." (PMID 37877343, 2023). "The disruption of the CUL7 E3 ubiquitin ligase complex induces cellular senescence, which contributes to the growth restriction in 3M syndrome." (PMID 41234413, 2025). "Our study expands the spectrum of CUL7 mutations and, for the first time, demonstrates the effectiveness of PGT‐M in preventing 3M syndrome." (PMID 37877343, 2023). "In conclusion, we identified novel truncating mutations of CUL7 and OBSL1 in Chinese patients with 3M syndrome." (PMID 37719700, 2023). "With the development of gene diagnosis technology, variants in the CUL7, OBSL1, and CCDC8 genes have been identified as responsible for 3M syndrome." (PMID 37719700, 2023). "3M syndrome is caused by mutations in three genes (Obscurin-like 1 [OBSL1]; Cullin 7 [CUL7]; Protein 8-containing helix-coiled domain [CCDC8])." (PMID 37520055, 2023). "Genetically confirmed patients with 3M syndrome carry mutations in CCDC8 (5%), OBSL1 (25%) or CUL7 (70%)." (PMID 32235515, 2020). "Mutations in CUL7, OBSL1 and CCDC8, leading to disordered ubiquitination, cause one of the commonest primordial growth disorders, 3-M syndrome." (PMID 24711643, 2014).
3M syndrome (continued). "Variants of uncertain significance in CUL7 were deemed unrelated, as the phenotype of 3M syndrome does not overlap with this case." (PMID 41531943, 2026). "In summary, this case report described a Chinese patient with 3M syndrome caused by biallelic pathogenic variants in CUL7 from a non-consanguineous family." (PMID 41234413, 2025). "It is conceivable that the growth retardation characteristic of the 3M syndrome as well as global Cul7- and Fbxw8-knockout mice can be explained by the regulatory function of CRL7 in the heart and the Hippo–YAP signaling pathway; however, additional investigation will be required to confirm this." (PMID 38334627, 2024). "Interestingly, the germline deletion of Cul7 has a global impact on growth, recapitulating the symptoms of 3M syndrome." (PMID 38334627, 2024). "The CUL7, OBSL1, and CCDC8 genes are exclusively mutated in 3-M syndrome." (PMID 33130829, 2020). "3M syndrome is a rare disorder that involves the gene cullin-7 (CUL7)." (PMID 32235515, 2020). "3‐M syndrome is classified into types I, II, and III, which have been identified to be associated with the exclusive variants in cullin 7 (CUL7; MIM *609577), obscurin‐like 1 (OBSL1; MIM *610991), and coiled‐coil domain‐containing protein 8 (CCDC8; MIM *614145) genes, respectively." (PMID 32141654, 2020). "Since CUL7 is involved in chondrocyte growth and proliferation, in 3-M syndrome, reduced cell mitosis during the early gestation period could be the cause of retarded growth." (PMID 23517720, 2013). "Functional experiments to verify R1445X and H1464P in CUL7 mutations showed that proteins with these two mutations cannot recruit ROC1 to form a complex, indicating that loss of ubiquitination may be the main pathological mechanism underlying 3M syndrome." (PMID 37719700, 2023). "The prevalence of 3M syndrome has not yet been clearly defined, but pathogenic variants of three genes, namely, CUL7 (3M1, MIM #273750), OBSL1 (3M2, MIM #612921), and CCDC8 (3M3, MIM #614205), were responsible for 77.5%, 16%, and <5% of 3M syndrome cases, respectively." (PMID 37877343, 2023). "Finally, the diagnosis of 3-M syndrome was made, confirmed by the analysis of the CUL7 gene." (PMID 23517720, 2013). "Thus, although FBXW8 has not been found to be mutated in 3M syndrome patients, the CUL7 mutations at the interface with FBXW8 may suggest a role in the function of the 3M E3 ligase complex." (PMID 35982156, 2022). "An intriguing recent finding is that Cul7-Fbw8 can degrade the insulin receptor substrate 1 (IRS-1) through Skp1-Fbw8-ROC1 (SCF complex), suggesting the mechanism of 3-M syndrome is related to IRS-123." (PMID 26423533, 2015). "In this study, we have used proteomic and transcriptomic approaches to identify the putative interacting partners of CUL7, OBSL1 and CCDC8 to create a 3-M syndrome interactome." (PMID 24711643, 2014). "While CUL7 and OBSL1 account for ~94% of known 3-M syndrome cases, the remaining 6% (at least partly accounted for by CCDC8 mutations) of undiagnosed cases suggests that additional genes and perhaps regulatory (non-coding) mutations in known genes are yet to be implicated." (PMID 25923536, 2015). "We postulate that the interactions of the 3-M proteins we have identified may link the disruption of CUL7 SCF substrate ubiquitination and their subsequent accumulation in 3-M syndrome to alteration of major splicing events." (PMID 24711643, 2014). "Whether there is any connection between OBSL1 recruitment of CUL7 to the Golgi and growth retardation in 3 M Syndrome is not known." (PMID 23029530, 2012).
breast carcinoma (8 papers, 2014 to 2024). "The arithmetic mean, standard deviation, and median values of salivary Cul7 gene expression levels were calculated as 10.1 ± 42.85; 0.66 in patients with breast cancer and 5.85 ± 17.7; 1.27 in controls." (PMID 39852134, 2024). "Mean (x), standard deviation (sd), and median values (m) of plasma Cul7 gene expression levels were calculated as 41.13 ± 80.41; 3.08 and 8.72 ± 14.85; 1.04 in breast cancer patients and healthy female controls, respectively." (PMID 39852134, 2024). "The mean (x), standard deviation (sd), and median (m) values of plasma protein Cul7 were found to be 4.93 ± 4.8; 3.12 ng/mL and 3.69 ± 2.48; 2.8 ng/mL in breast cancer patients and female healthy controls, respectively." (PMID 39852134, 2024). "Plasma Cul7 protein levels are above the median value (m = 3.12, m = 2.8, respectively) in breast cancer patients and healthy control groups." (PMID 39852134, 2024). "Plasma Cul7 gene expression levels are above the median value (m = 3.08, m = 1.04, respectively) in breast cancer patients and healthy control groups." (PMID 39852134, 2024). "Salivary Cul7 protein levels show a distribution close to the median value (m = 2.25) in patients with breast cancer, while it is above the median value (m = 1.9) in the healthy control group." (PMID 39852134, 2024). "Based on this information, we aimed to determine the gene expression and protein levels of the Cul7 molecule in plasma and saliva samples of patients with breast cancer." (PMID 39852134, 2024). "In this study performed in breast cancer tissues, Cul7 protein levels were compared with normal breast tissues, and it was determined that Cul7 expression was significantly higher in breast cancer samples (p < 0.01 is based on Student’s t-test)." (PMID 39852134, 2024). "Although plasma and salivary protein Cul7 levels in breast cancer patients were higher than in the healthy control group, the difference was statistically insignificant (p = 0.463, p = 0.938)." (PMID 39852134, 2024). "In this study, the levels of the Cul7 molecule in plasma and noninvasive material saliva were investigated, and its possibility as a marker for breast cancer was discussed." (PMID 39852134, 2024). "Qiu further analyzed the clinical significance of CUL7 in breast cancer tissue, and noted the mechanisms of CUL7 in the invasion and migration of breast cancer cells." (PMID 33130829, 2020). "In our study, when Cul7 gene expression levels in plasma and saliva samples of breast cancer patients and healthy controls were compared, although the plasma samples were found to be higher in the patients than in the control group, statistical insignificance was detected between them (p > 0.05)." (PMID 39852134, 2024). "The role of the Cul7 molecule in breast cancer is still unclear, and understanding its function could have significant implications for identifying novel therapeutic targets or improving diagnostic strategies in breast cancer management." (PMID 39852134, 2024). "In our study, Cul7 mRNA and protein expression levels were examined in 60 breast cancer patients and 20 healthy female controls, and a statistically insignificant difference was found between the patient and control groups in both plasma and saliva samples (p > 0.05)." (PMID 39852134, 2024). "Also, salivary Cul7 gene expression levels show a distribution above the median value (respectively; m = 0.66, m = 1.27) in breast cancer patients and healthy control groups." (PMID 39852134, 2024). "Therefore, it is thought that Cul7 functions as a novel oncogene in breast cancer and provides evidence that it could be a potential therapeutic target." (PMID 39852134, 2024).